FOXJ1 (forkhead box J1)
Diseases named in the same sentence as FOXJ1 in open-access papers (continued):
Sharing a sentence is not in itself a finding about the gene and the disease.
endometrial cancer (3 papers, 2022 to 2025). Primary or metastatic malignant neoplasm involving the endometrium (mucous membrane that lines the endometrial cavity). "Moreover, FOXJ1 expression has been reported to be associated with a favorable prognosis in high grade serous carcinomas and endometrial carcinomas." (PMID 39936988, 2025). "Single-cell sequencing of endometrial and ovarian tumours has shown that FOXJ1 is expressed in endometrial tumours and is positively correlated with the disease specificity and overall survival of endometrial cancer patients." (PMID 35292033, 2022). "Instead, the expression of the ciliated marker FOXJ1 in HGSC can be considered as a marker of enigmatic differentiation, which does not result in morphologically apparent cilia and is associated with better outcome; a phenomenon that has been previously suggested for endometrial cancers." (PMID 36323878, 2023).
Autoimmunity (2 papers, 2018 to 2022). The occurrence of an immune reaction against the organism's own cells or tissues. "FOXJ1 can impair autoimmunity as it is a modulator of Th1 activation, with its deficiency resulting in autoimmunity due to a role in antagonizing NFκB activity." (PMID 35328504, 2022). "Previous studies showed that FoxJ1 mediates multiple physiological processes, especially ciliogenesis, embryonic development, spontaneous autoimmunity inhibition, and malignancy." (PMID 29850474, 2018).
colon cancer (2 papers, 2018 to 2020). "Additionally, FOXJ1 is a significant transcription factor in the central nervous and reproductive systems and overexpression of FOXJ1 has been reported to be highly associated with colon cancer stage and its outcome." (PMID 30111286, 2018).
congenital hydrocephalus (2 papers, 2021 to 2023). Hydrocephalus that is present at birth. "Until now, the majority of published de novo mutations in FOXJ1 have been loss of function mutations (stop gain codons), and there was also a missense mutation that was related to a case of congenital hydrocephalus." (PMID 37620636, 2023). "Recently, a large genetic study on congenital hydrocephalus reported 3 unrelated cases harboring heterozygous variants in FOXJ1." (PMID 34132502, 2021).
COVID-19 (2 papers, 2021 to 2022). A disease caused by infection with severe acute respiratory syndrome coronavirus 2. "Here, we show that the changes observed in the hamster trachea mirror alterations occurring in humans, including limited cell death and the loss of FOXJ1, confirming the value of the model to study the pathogenesis of COVID-19." (PMID 35563514, 2022). "Loss of cilia and FOXJ1 protein expression has also been shown in samples from COVID-19 patients." (PMID 35563514, 2022). "ULBP2, SYT2, VMAC, and FOXJ1 followed the same pattern of expression in COPD compared to COVID-19, however, to a much lower level." (PMID 33679887, 2021). "The expression of FOXJ1 was decreased in COVID-19 lung biopsies." (PMID 33679887, 2021).
emphysema (2 papers, 2023 to 2025). "Certain studies demonstrated that rhCC16 could limit the progression of emphysema in mice through a reduction in the activity of NF‐kappa B in CC16‐knockout lung tissues stimulated by CSE and the rescue of decreased Foxj1 expression." (PMID 40259209, 2025).
laryngeal squamous cell carcinoma (2 papers, 2021 to 2022). A squamous cell carcinoma that arises from the larynx. "Knockdown of FOXJ1 inhibits proliferation, migration, invasion and glycolysis in laryngeal squamous cell carcinoma cells." (PMID 35292033, 2022). "Highly expressed FOXJ1 promoted the proliferation and invasiveness of laryngeal squamous cell carcinoma cells." (PMID 34109184, 2021).
lung fibrosis (2 papers, 2022 to 2023). "To elucidate the physiological role of p300 in lung epithelial cells during the development of pulmonary fibrosis, we generated genetically engineered mouse models with tamoxifen-inducible p300 knockout in ATII cells (Spc-p300d/d), club cells (Ccsp-p300d/d), or ciliated cells (Foxj1-p300d/d)." (PMID 37524875, 2023).
respiratory infections (2 papers, 2021 to 2026). "The findings establish a protective role for the gut microbiome-derived valeric acid in respiratory infections via the novel HDAC-Wnt-FOXJ1 axis, revealing its potential as a therapeutic agent to improve clinical outcomes." (PMID 41601983, 2026).
serous carcinomas (2 papers, 2022 to 2025). "The mean FOXJ1 expression in borderline serous tumors was 7.568 compared to 6.867 in serous carcinomas (p = 2.35 × 10−16)." (PMID 36552773, 2022). "Both FOXJ1 and CAPS expression levels differed markedly between serous borderline tumors and serous carcinomas." (PMID 36552773, 2022).
situs inversus (2 papers, 2023 to 2024). A congenital condition in which there is complete right-to-left reversal of the position of the major thoracic and abdominal organs (that is, they are arranged in a mirror image of the normal positioning). "Homozygous or heterozygous deletion of FOXJ1 leads to situs inversus and mucociliary clearance dysfunction in humans and mice." (PMID 37620636, 2023).
Stroke (2 papers, 2018 to 2020). Sudden impairment of blood flow to a part of the brain due to occlusion or rupture of an artery to the brain. "Taken together, our results indicate minimal, if any, direct cellular contribution from the Foxj1+ ependymal cell pool to sites of insult or other forebrain regions after injury and stroke." (PMID 29379049, 2018). "Non stem- and progenitor-like responses of Foxj1+ ependymal cells to injury and stroke remain to be defined and investigated." (PMID 29379049, 2018). "Using a cell specific genetic approach we rule out Foxj1+ ependymal cells as stem cells participating in neurogenesis and gliogenesis in response to acute injury or stroke in the mouse forebrain." (PMID 29379049, 2018). "Even though the current findings rule out Foxj1-expressing ependyma as a source of new cells in response to injury and stroke, the role of ECs in homeostasis of the brain and their cellular responses to injury, disease, and aging are beginning to be deciphered." (PMID 29379049, 2018). "In one study, intraventricular injections of adeno or lenti viruses driving expression of reporters downstream of the human FOXJ1 promoter resulted in labeling of new cells generated from transduced cells only after induction of stroke but not in naïve adult mice." (PMID 29379049, 2018). "We did not test the response of the FoxJ1+ VZ population during Ara-C–induced niche regeneration, as we had for electroporated cells; however, a recent study using this lineage-tracing model showed no significant neurogenic response in brain injury/stroke models." (PMID 32482782, 2020).
breast tumor (1 paper, 2020). "FOXJ1, also known as HNF-4, is thought to inhibit tumor growth by resisting NF-κB activity, and FOXJ1 is ubiquitous in hypermethylated tumors and it is suggested that FOXJ1 silencing is an important potential factor in breast tumor formation." (PMID 32742463, 2020).
cervical cancer (1 paper, 2025). A primary or metastatic malignant neoplasm involving the cervix. "Collectively, these findings indicate that FOXJ1 exerts tumor-suppressive effects in cervical cancer by inhibiting cuproptosis, thereby reducing cellular proliferation, invasion, and migration." (PMID 41142609, 2025). "Thirdly, although FOXJ1 has been shown to regulate the growth of cervical cancer cells through cuproptosis, the in vivo validation and molecular mechanism exploration are still needed in the future." (PMID 41142609, 2025). "To further validate the reliability of the constructed cuproptosis model, we selected the FOXJ1 gene and validated its effect on the growth of cervical cancer cells." (PMID 41142609, 2025). "Overexpression of FOXJ1 promoted cuproptosis in cervical cancer cells and further inhibited their proliferation, migration, and invasion." (PMID 41142609, 2025). "FOXJ1 promoted cuproptosis in cervical cancer cells, thereby inhibiting their proliferation, migration, and invasion capabilities." (PMID 41142609, 2025). "To verify our previous results, we selected FOXJ1 and tested its effect on the growth of cervical cancer cells." (PMID 41142609, 2025). "The Transwell assay showed that the invasion and migration ability of cervical cancer cells decreased significantly after FOXJ1 over expression." (PMID 41142609, 2025). "FOXJ1 significantly enhances the cuproptosis of cervical cancer cells, thereby effectively inhibiting their proliferation, invasion, and migration capabilities through the activation of this cell death pathway." (PMID 41142609, 2025). "Our findings showed that FOXJ1 overexpression in cervical cancer significantly inhibited the proliferation and colony formation capacity of cervical cancer cells and significantly weakened their invasion and migration ability." (PMID 41142609, 2025). "Thus, FOXJ1 could affect the invasion and migration of cervical cancer cells through the regulation of the EMT process." (PMID 41142609, 2025). "However, the role of FOXJ1 in cervical cancer remains unclear." (PMID 41142609, 2025). "Moreover, the overexpression of FOXJ1 (one of the DEGs) significantly decreased the proliferation, invasion, migration and Epithelial-Mesenchymal Transition (EMT) process in cervical cancer cells." (PMID 41142609, 2025).
chronic kidney disease (1 paper, 2022). Impairment of the renal function secondary to chronic kidney damage persisting for three or more months. "AL353637.1 is a pseudogene nearby the gene FOXB2, also belongs to the FOX family of FOXJ1, and contains a variant (rs115747230) associated with chronic kidney disease." (PMID 35565241, 2022).
co-infection (1 paper, 2022). "We found FOXJ1 mRNA levels to be decreased in co-infection with the non-mucoid PA isolate, compared to virus-infection alone (0.31 ± 0.17 fold change vs. 1.14 ± 0.49 fold change, p=0.002)." (PMID 35265536, 2022). "After co-infection with HRV and the non-mucoid PA isolate, we detected lower mRNA levels of Forkhead box J1 (FOXJ1) and Cilia Apical Structure Protein (SNTN), markers of epithelial cell differentiation to ciliated cells." (PMID 35265536, 2022).
congenital obstructive hydrocephalus (1 paper, 2023). "Although de novo heterozygous FOXJ1 mutation is associated with congenital obstructive hydrocephalus in humans, mice with heterozygous Foxj1 mutations did not display the domed head and perinatal death that is frequently associated with congenital obstructive hydrocephalus in mice." (PMID 37620636, 2023).
endometriosis (1 paper, 2018). The growth of functional endometrial tissue in anatomic sites outside the uterine body. "Here, we identified four important FOX subfamily members, FOXO1, FOXC1, FOXL1 and FOXJ1, which cooperatively regulate the integrative networks in endometriosis." (PMID 29357938, 2018).
infertile (1 paper, 2017). "In stark contrast, FOXJ1-Cre;CEP164fl/fl males were completely infertile." (PMID 29244804, 2017).
invasive carcinoma (1 paper, 2025). A carcinoma that is not confined to the epithelium, and has spread to the surrounding stroma. "Analysis of FOXJ1 in 214 ER-positive invasive carcinomas demonstrated protein expression in one third of tumors, suggesting frequent focal MCC differentiation." (PMID 39936988, 2025).
lobular carcinomas (1 paper, 2025). "No statistical associations were observed when analyses were performed with a threshold of 5% of FOXJ1 positive cells and separately for ductal and lobular carcinomas." (PMID 39936988, 2025).
male infertility (1 paper, 2022). The inability of the male to effect fertilization of an ovum after a specified period of unprotected intercourse. "FOXJ1-Cre;Cep164fl/fl mice show a profound loss of airway, ependymal, and oviduct multicilia and develop hydrocephalus and male infertility." (PMID 35159149, 2022). "MCC-specific inactivation of miR-34/miR-449 using a FOXJ1-Cre driver phenocopies the ED deficits of the germline miR-34b/c−/−/miR-449−/− male mice, reinforcing the view that loss of multicilia in the EDs is the primary cause of their male infertility." (PMID 35159149, 2022).
metastatic tumors (1 paper, 2022). "Using the “HGSOC Progression” TMA, we compared the percentage of 42 patient-matched primary, synchronous metastatic, and metachronous/recurrent metastatic tumors for the presence of FOXJ1+ and/or CAPS+ cells." (PMID 36552773, 2022).
mucinous tumors (1 paper, 2022). "Most mucinous tumors expressed relatively low mRNA levels of ciliated cell markers FOXJ1 and CAPS and there was a clear dichotomy in PAX8 mRNA expression when mucinous EOC were compared to serous, endometrioid, and clear cell EOC." (PMID 36552773, 2022). "Of note, mucinous tumors expressed low levels of both ciliated cell (FOXJ1, CAPS) and secretory cell (PAX8) cell markers, possibly suggesting a different cell of origin for this histologic subtype." (PMID 36552773, 2022).
pneumonia (1 paper, 2026). An acute, acute and chronic, or chronic inflammation focally or diffusely affecting the lung parenchyma, caused by an infection in one or both of the lungs (by bacteria, viruses, fungi, or mycoplasma.). "Consistent with this, our multifaceted evidence indicates that impaired ciliary function is an important driver of severe pneumonia progression, which activation of FOXJ1 and its upstream pathways can restore MCC-mediated defense." (PMID 41601983, 2026). "Mechanistically, valeric acid enhanced ciliary biogenesis and function by inhibiting HDAC3, activating Wnt signaling, and upregulating FOXJ1, which ultimately improved clinical outcomes in severe pneumonia." (PMID 41601983, 2026).
tumor (31 papers, 2010 to 2025). "Reintroduction of either Gmnc or Mcidas activated the expression of TAp73 and Foxj1 and caused multiciliation of tumor cells." (PMID 35322202, 2022). "Prognosis was most favourable in tumours with >50% of cells expressing FOXJ1 (HR 0.78, 95% CI 0.67–0.91, p < 0.05), with the 5-year survival being >10% higher than those without expression." (PMID 36323878, 2023). "Tumor cells in these mice were monociliated and exhibited significantly reduced Gmnc and Foxj1 levels." (PMID 35322202, 2022). "Results from these assays consistently showed that both Foxj1 and Mcidas were expressed in tumor cells at lower levels than observed in wild type CP epithelium." (PMID 35322202, 2022). "Consistently, tumor cell proliferation was markedly reduced, and the expression of Foxj1 was significantly increased by IMR-1." (PMID 35322202, 2022). "FOXJ1 target genes that mediate ciliogenesis are enriched in the ST-YAP cluster, consistent with a cilia-associated program hallmark of this tumor." (PMID 34885210, 2021). "In order to determine which cells within the tumor were proliferating, we co-stained sections for phosphohistone-H3 and p63 or FoxJ1." (PMID 20548776, 2010). "Consistently, the expression of multiciliation regulators Gmnc, TAp73, and Foxj1, as well as CP epithelial markers Ttr and Aqp1, were significantly reduced in tumor cells irrespective of Sox2 loss." (PMID 40128799, 2025). "“Aberrant” FOXJ1 expression in HGSC may reflect epigenetic reprogramming of secretory cell-derived tumour cells or a unique differentiation state of the cell of origin." (PMID 36323878, 2023). "Patients with tumours with >50% of cells expressing FOXJ1 had the longest survival." (PMID 36323878, 2023). "Conversely, expression of transcripts encoding the tumor suppressors Dmp1 and Foxj1 was suppressed by Src and increased by contact normalization." (PMID 35177067, 2022). "Conversely, overexpression of Gmnc increased Foxj1 expression in tumor cells." (PMID 35322202, 2022). "For example, miR-31 inhibits tumour invasion and metastasis by targeting RhoA in human GC; miR-6852 suppresses cell proliferation and invasion by targeting forkhead box J1 (FOXJ1) in GC; and miR-618 restricts metastasis in GC by downregulating the expression of TGF-β2." (PMID 31423109, 2019). "Analysis of the promoter methylation levels of the 15 DE-FOXs by UALCAN revealed downregulation of the promoter methylation levels of FOXD1, FOXJ1, and FOXK1 in tumor tissues." (PMID 36622275, 2023). "Tumor cells from Lcre;NICD1;Gmncflox/− mice became resistant to multiciliation, Foxj1 activation, and decreased proliferation induced by IMR-1/IMR-1A." (PMID 35322202, 2022). "FOXJ1 and CAPS expression levels also decreased with increasing tumor grade while PAX8 levels increased with tumor grade." (PMID 36552773, 2022). "In our data, the expression of epithelial cilium movement markers, including FOXJ1, PRG, RFX2, and TMF1, although increased during the process, were mainly overexpressed in primary tumor cells." (PMID 35935940, 2022). "FOXJ1 is hypermethylated in BRCA cell lines and clinical tissue samples, revealing its role as a putative tumor suppressor gene." (PMID 33688372, 2021). "Assessment of epithelial marker genes showed similar expression scores across fresh and FFPE tissue samples, as EPCAM, KRT5, SCGB3A2, FOXJ1, AGER and SFTPC marked tumor epithelial, Basal, Transitional, Ciliated, AT1, and AT2 cells, respectively, across the datasets." (PMID 38300468, 2024). "The downregulated mRMR genes for normal versus tumor samples are DPP6 and FOXJ1." (PMID 35565241, 2022). "KRT5+ basal cells did not produce any tumours, whereas ciliated (Forkhead box J1, FOXJ1+) and alveolar Type II (Surfactant protein C, SFTPC+) gave rise to LUAD." (PMID 34354223, 2021). "In-Patient 2, non-canonical deleterious variants in FOXJ1, PRKDC, and TTN were detected in ~100% CCF across all tumor samples." (PMID 34400647, 2021).
tumor (continued). "For instance, the expression of the ciliated epithelial markers, including FOXJ1, PIGR, CAPS, and GDF15, declined during the process of metastasis, although they were overexpressed in EC2 that mainly consisted of primary tumor cells." (PMID 34459128, 2021). "Compared to normal samples, the expression of E2F2, FOXJ1, EMX1, PAX7, NKX6-1, FOXD1, and ZNF552 was significantly higher (P < 0.05) and the expression of MSX1, STAT4, NR3C2, and EGR3 was significantly lower in tumor samples (all P < 0.05)." (PMID 33688372, 2021). "For instance, according to single-cell DE analysis, TFs such as TBX4 and FOXJ1, both with important roles in lung tissue development, were not underexpressed in tumor cells, yet they were found to be inactivated according to SCIRA." (PMID 33083012, 2020). "Similarly, no threshold effects were observed, such as any expression of FOXJ1 conferring better outcomes in comparison to tumours having no expression of the protein." (PMID 36323878, 2023). "In addition, all tumours developed in Foxj1 mice were negative for GFP (0 out of 113 analysed tumours)." (PMID 35931677, 2022).